FABP5 (fatty acid binding protein 5)
Diseases named in the same sentence as FABP5 in open-access papers (continued):
Sharing a sentence is not in itself a finding about the gene and the disease.
tumor (continued). "FABP5 promotes growth in osteosarcoma through the Akt/mTOR pathway and mediates therapy resistance in medulloblastoma, underscoring its role in tumor survival and progression." (PMID 40370434, 2025). "The results further demonstrated that nanocarriers targeting FABP5 effectively remodeled the anti‐tumor immune response in HCC." (PMID 40956367, 2025). "FABP5 inhibitors such as SBFI-26 suppress tumor cell proliferation and invasion by inducing ferroptosis or enhancing chemotherapeutic sensitivity, showing therapeutic potential." (PMID 40717587, 2025). "FABP5 facilitates tumour growth by modulating key signalling pathways, such as PI3K/AKT, MAPKs, and NF-κB, particularly within inflammatory and lipid-rich tumour microenvironments mimicked by adipocyte-conditioned medium (aCM)." (PMID 41149452, 2025). "It has been also shown that FABP5 supports tumour survival under hypoxic or nutrient-deprived conditions via a FABP5–HIF-1α axis that upregulates both hypoxia-responsive and lipid metabolism genes." (PMID 41149452, 2025). "In summary, ICT appears to function through a dual regulatory strategy: “suppressing malignancy” by downregulating pro-oncogenic genes (CA9, UCK2, and FABP5), and “reinforcing physiological function” by upregulating the potential tumor suppressor CYP2C9." (PMID 41357200, 2025). "Macrophages in dead tissue areas, which are rich in lipids and highly express CD36 and FABP5, transfer fatty acids to nearby tumor cells." (PMID 40904700, 2025). "The proposed nanocarrier integrates cyclic arginine‐glycine‐aspartic acid (cRGD) and red blood cell membrane (RBCM), encapsulating superparamagnetic iron oxide (SPIO) to specifically target fatty acid‐binding protein 5 (FABP5) in tumor cells." (PMID 40956367, 2025). "Despite the robust evidence for tumor-derived FABP5-mediated macrophage reprogramming, it is essential to recognize that immune modulation in tumors is inherently multifactorial." (PMID 41035647, 2025). "Recent studies suggest that the fatty acid-binding protein (FABP5) exerts age-dependent effects in tumor biology." (PMID 40370434, 2025). "Elevated FABP5 expression is positively correlated with tumor metastasis and decreased patient survival, suggesting that FABP5 functions as an intrinsic lipid chaperone, promoting lipid metabolism and tumor dissemination." (PMID 40106183, 2025). "It directly binds to key lipid metabolism targets, including fatty acid-binding protein 5 (FABP5), which promotes lipid droplet accumulation and tumor invasion, and α-1B adrenergic receptor (ADRA1B), which regulates fatty acid synthase activity." (PMID 41019994, 2025). "Experimental evidence demonstrates that genetic suppression of FABP5 attenuates tumor growth in preclinical models, whereas LA-bound FABP5 exacerbates it." (PMID 41583314, 2025). "Genetic ablation of FABP5 disrupts these processes, attenuating tumor growth and immunosuppression in preclinical models." (PMID 41035647, 2025). "The anti‐tumor immune effects of FABP5‐targeting co‐delivery nanoparticles combined with RFA were further examined in HCC." (PMID 40956367, 2025). "Our previous study showed that FABP5, also through NF-κB signaling pathway activation induced by excessive fatty acid, stimulated tumor cell epithelial-mesenchymal transition (EMT), invasion and lymphangiogenesis in CCa21." (PMID 41049446, 2025). "The nanocarrier targeting tumor cell‐intrinsic FABP5 resulted in the downregulation of HMGB1 expression, thereby amplifying the ICD induced by RFA." (PMID 40956367, 2025). "FABP5 (fatty acid-binding protein 5) plays a key role in lipid metabolism and is involved in promoting tumor cell survival, immune evasion, and drug resistance by modulating metabolic and inflammatory signaling pathways." (PMID 40723181, 2025).
tumor (continued). "Unlike previous studies primarily focusing on the endogenous functions of FABP5 within tumor cells, this research innovatively reveals that tumor cells can “export” FABP5 via exosomes to directly affect the metabolism and function of immune cells in the TME." (PMID 41035647, 2025). "In a murine tumor xenograft model, FABP5 knockout significantly impeded tumor growth, as reflected by reduced tumor volume and weight compared to WT controls." (PMID 41035647, 2025). "FABP5 orchestrates pro‐proliferative, survival, and invasive signaling cascades within tumor cells, while concurrently modulating the immunosuppressive tumor microenvironment through perturbation of immune cell lipid metabolism." (PMID 40956367, 2025). "FABP5 facilitates tumor cell proliferation and metastasis by modulating the PPAR β/δ signaling pathway and stabilizing epidermal growth factor." (PMID 40178066, 2025). "The tumor inhibition effect of FABP5 knockdown was found to be similar to that of MELK knockdown in the Hepa1-6 subcutaneous tumor bearing model." (PMID 39871325, 2025). "FABP5 is primarily expressed in epithelial cells, macrophages, and stromal cells within the tumor microenvironment." (PMID 40717587, 2025). "Tumor-infiltrating CER-TAGLN2 T cells maintained high TAGLN2 expression and surface levels of FABP5 compared to control CER T cells present at the same tumor sites." (PMID 39948077, 2025). "Highly expressed in both cancer cells and anti-inflammatory macrophages, FABP5 inhibition promotes lipid peroxidation-induced ferroptosis in tumor cells while reprogramming TAMs toward a proinflammatory phenotype." (PMID 40507339, 2025). "Inhibiting FABP5 disrupts lipid signaling pathways essential for tumor cell growth, potentially impairing cancer progression." (PMID 40426875, 2025). "In contrast, the highly immunogenic and microbially influenced colorectal environment appears to shift FABP5 activity towards mTOR-mediated autophagy and anti-tumor effects." (PMID 40717587, 2025). "This immunosuppressive shift enhances MMP2 secretion and supports tumour metastasis, while restoring FABP5 reverses these effects." (PMID 41149452, 2025). "This study elucidates a critical role for HCC-derived exosomal FABP5 in reprogramming macrophage lipid metabolism to drive immunosuppressive polarization and tumor progression." (PMID 41035647, 2025). "Research indicates that FABP5 is a target gene involved in the regulation of tumorigenesis and tumor progression in tumor cells influenced by both saturated and unsaturated fatty acids." (PMID 40178066, 2025). "Although FABP5 knockout significantly enhances the anti‐tumor efficacy of RFA, the in vivo instability of the sgFABP5 plasmid limits its clinical applicability." (PMID 40956367, 2025). "Flow cytometry analysis revealed significant increases in CD80+CD86+ DCs, CD8+CD3+ T cells, and CD44+CD62L‐TEM cells, indicating that FABP5 inhibition effectively enhanced immune responses in the tumor microenvironment." (PMID 40956367, 2025). "In liver-specific FABP5 knockout mouse models and HCC xenograft models, FABP5 deletion significantly suppressed tumor growth, reduced M2-type TAM infiltration and lipid accumulation, and enhanced anti-tumor immune responses." (PMID 41035647, 2025). "SBFI26, an inhibitor of FABP5, has been shown to suppress the proliferation and metastasis of tumour cells." (PMID 38516826, 2024). "Chen et al35 reported that in LAUD, CCAT1/FABP5 promotes tumour progression by mediating fatty acid metabolism and stabilizing PI3K/AKT/mTOR signalling." (PMID 38506080, 2024). "Intriguingly, our prior research has illustrated that elevated levels of FABP5 in pNEN cells enhance tumor proliferation and metastasis." (PMID 38904015, 2024). "As one member of fatty acid binding proteins (FABPs), FABP5 makes a contribution in the occurrence and development of several tumor types, but existing analysis about FABP5 and FABP5-related molecular mechanism remains limited." (PMID 36906605, 2023).
tumor (continued). "As the tumor progresses, FABP5 expression increased in the cases of CESC and KIRC, but decreased in BLCA." (PMID 36906605, 2023). "We verified FABP5 overexpression in many tumor types, and partial results obtained support by previous studies." (PMID 36906605, 2023). "We also identified Fabp5 as a specific marker of tumor-promoting neutrophils and found that it was associated with a dismal prognosis in the TCGA-SKCM and GSE65904 SKCM datasets." (PMID 36650153, 2023). "Pharmacological or genetic FABP5 inhibition reduces PC survival, tumor growth, and metastasis, thus positioning FABP5 as a promising therapeutic target." (PMID 37796964, 2023). "Taken together, we made a pan-cancer analysis of FABP5 based on TCGA and GTEx database for the first time, and confirmed FABP5 overexpression in most tumor types." (PMID 36906605, 2023). "We conducted expression analysis of FABP5 in multiple tumor types with sufficient normal tissues (more than five cases) in TCGA project." (PMID 36906605, 2023). "Conversely, SW620 cells with stable FABP5 knockdown showed accelerated tumor growth compared with the control group, which was suppressed by orlistat." (PMID 37416772, 2023). "More recently, FABP5 in monocytes/macrophages was shown to promote lipid accumulation and induction of the inhibitory tumor microenvironment of HCC." (PMID 36959981, 2023). "For further understanding of FABP5-related molecular mechanism in multiple tumor types, more ceRNA regulatory networks need to be explored." (PMID 36906605, 2023). "Survival analysis was also conducted by the Kaplan–Meier survival curve and Log-rank test in those tumor types with FABP5 overexpression." (PMID 36906605, 2023). "As one member of this family, FABP5 presents unique characteristics in various specific cells and tissues including adipocytes, macrophages and tumor cells." (PMID 36906605, 2023). "FABP5 is highly expressed in various cancers and closely related to tumor growth, development and metastasis." (PMID 37416772, 2023). "In sharp contrast, total FABP5 expression in the same CD8+ T cells analyzed increased throughout tumor progression." (PMID 38168227, 2023). "Clinical data demonstrated worse overall and progression-free survival in patients with high FABP5 expression in tumor cells." (PMID 36880649, 2023). "FABP5 showed the most significant correlation with tumor-infiltrating immune subsets, such as B-cells, CD4+ T-cells, CD8+ T-cells, neutrophils, macrophages, and dendritic cells." (PMID 36950134, 2023). "High FABP5 expression levels in tumor-infiltrating Tregs enhance mitochondrial disturbances, type I IFN signaling, and immunosuppressive activity." (PMID 37545500, 2023). "FABP5 expression also plays a role in preventing cell cycle arrest, followed by the continuous division of cells, resulting in tumor development." (PMID 37645246, 2023). "Jin, R and colleagues demonstrated that the long-chain fatty acid, linoleic acid, induced mitochondrial ROS accumulation via FABP5 to impair the anti-tumor immune T-cell response." (PMID 36875092, 2023). "Based on these results, we proposed that NBASP played an anti-tumor role through negatively regulated FABP5." (PMID 37438449, 2023). "Data from the transwell assay showed that FABP5 silencing facilitated migration and invasion of HCT116 and SW620 cells, supporting a tumor suppressor role of FABP5 in CRC cells." (PMID 37416772, 2023). "Intriguingly, we identified the ability of FAM201A to encode the tumor-suppressing protein, NBASP, which interacted with FABP5 and negatively regulated its expression." (PMID 37438449, 2023). "To date, many studies have reported that ceRNA networks play a great role in multiple tumor types, providing a direction for exploring potential FABP5-related molecular mechanism." (PMID 36906605, 2023). "Data from functional assays revealed inhibitory effects of FABP5 on cell proliferation, colony formation, migration, invasion as well as tumor growth in vivo." (PMID 37416772, 2023).
tumor (continued). "To establish the precise function of FABP5 in cancer, we investigated its expression patterns in various tumor types." (PMID 37416772, 2023). "The results revealed that KRT13+FABP5+ malignant cell subpopulation had keratinization characteristics in the tumor tissue." (PMID 37124494, 2023). "Considering the known contribution of FABP5 to PC progression, these findings provide additional evidence that FABP5 inhibition is a sound therapeutic strategy to reduce tumor growth and metastasis and potentially blunt the development of taxane resistance." (PMID 37796964, 2023). "High cytoplasmic levels of FABP5 are crucial to enhance the anti-apoptotic activity and ultimately results in tumor growth and development of various cancers." (PMID 37645246, 2023). "Both silencing of FASN and treatment with FASN inhibitor inactivated the mTOR pathway, supporting a tumor suppressor role of FABP5 via inhibition of mTOR through FASN." (PMID 37416772, 2023). "In contrast, FABP5 in M1 macrophages enhances the recruitment of tumor-killer immune cells, such as effector T cells and NK cells, to the tumor site by inducing IFN-β secretion, thus promoting antitumor immune responses." (PMID 37545500, 2023). "Using TIMER2 approach, we explored the potential relationship between FABP5 expression and immune infiltrations in different tumor types." (PMID 36906605, 2023). "We previously demonstrated that docetaxel, when combined with FABP5 inhibitors, produces enhanced suppression of tumor growth compared to either agent alone." (PMID 37796964, 2023). "To identify the mechanism mediated by NBASP, we combined Co-IP and loss-and-gain functional experiments, and found that NBASP bound FABP5 when participating in its anti-tumor effect." (PMID 37438449, 2023). "Then we added normal tissues from GTEx database as controls, and further analyzed the difference of FABP5 expression between the normal and tumor tissues in other thirteen tumor types." (PMID 36906605, 2023). "The chemical inhibitor SBFI26 restricts tumor proliferation by targeting FABP5-PPARγ-VEGF signaling." (PMID 37545500, 2023). "Future studies should aim at further exploring the exact roles of FABP5 in anti-tumor immunological surveillance or in promoting tumor progression through lipid metabolism, and the balance between them." (PMID 35445019, 2022). "By analyzing the clinicopathological characteristics and clinical outcomes of the 48 HCC patients, we discovered that the expression of FABP5 was closely related to tumor staging and postoperative metastasis (p < .05)." (PMID 35816613, 2022). "PA-induced GC metastasis is achieved through FABP5/SP1/UCA1 signaling, and STAT5A increases the tumorigenic capacity of tumor cells by increasing FABP5 expression to regulate fatty acid metabolism." (PMID 35625633, 2022). "Mounting evidence has recently revealed the molecular mechanism by which FABP5 promotes tumor development." (PMID 35816613, 2022). "RT-qPCR analysis showed that miR-889-5p was significantly upregulated in tumor tissues, while miR-889-5p expression was negatively associated with KLF9 expression in HCC tissues and positively associated with FABP5 expression in HCC tissues." (PMID 35816613, 2022). "In line with this, FABP5 has been shown to convert the strong anticarcinogenic properties of retinoic acid (RA) into tumor-promoting functions as it delivers RA to the mitogenic and anti-apoptotic PPARβ/δ receptor." (PMID 35954274, 2022). "FABP5 promotes the production and signaling pathway of interferon β (IFNβ), thereby achieving tumor killing." (PMID 35445019, 2022). "FABP4 and FABP5 knockdown in GC cells significantly boosted lipid uptake in tissue-resident memory T cells (TRM) in a tumor cell–T cell co-culture system when compared to FABP4 or FABP5 knockdown alone." (PMID 35625633, 2022). "All these strong pieces of evidence prove that FABP5 is an important regulator of tumor cell proliferation." (PMID 35445019, 2022).
tumor (continued). "In TNBC patients, elevated levels of FABP5 were correlated with tumor grade and poor prognosis, and higher amounts of tumor FABP4 expression were associated with significantly shorter disease-free survival and overall survival." (PMID 34948368, 2021). "Hypoxia-inducible factor-1α, which is a transcription factor in the downstream of FABP5 signaling, reportedly promotes the residency and anti-tumor function of tumor-infiltrating T cells in the murine malignancy model." (PMID 34501272, 2021). "In summary, the proportional relationship between CRABP2 and FABP5 with tumor progression is still controversial." (PMID 34632074, 2021). "A previous study indicated that FABP5 promotes tumor angiogenesis and activates the VEGF-A pathway in HCC via the peroxisome proliferator-activated receptor d (PPARd)-dependent pathway." (PMID 34685761, 2021). "The results demonstrated that FABP5 was significantly enriched in LGGs compared to non‐tumour tissues, which is consistent with the results from western blot analysis." (PMID 33837625, 2021). "We also analyzed the expression of Krt10 and Fabp5, two highly expressed genes that had multiple MmuPV1 integration sites in tumor tissues and performed RNA ISH using RNAscope technology." (PMID 34343212, 2021). "Herein, in agreement with our previous study, we found that FABP5 was upregulated in the primary tumours of CCa with LNM and that its expression significantly was correlated with LNM." (PMID 32550890, 2020). "FABP5 expression in primary CCa tumours with LNM was significantly higher than that in tumours without LNM and normal uterine cervical tissues (NCTs) at both mRNA and protein levels." (PMID 32550890, 2020). "Our results indicated that FABP5 overexpression increased, while FABP5 knockdown decreased the tumour growth of CCa." (PMID 32550890, 2020). "To further assess the role of the FABP5/HIF-1α axis in tumor spheroid growth, we used an in vitro three-dimensional (3D) cell-culture system with si-FABP5 or si-HIF-1α-treated HepG2 cells." (PMID 33128030, 2020). "Subsequently, we examined their expression in paired normal and tumor tissues and found that the protein levels of FABP5 and HIF-1α were elevated in tumor tissues compared with adjacent normal tissue." (PMID 33128030, 2020). "Of note, they also observed decreased VEGF and micro-vessel densities in FABP5–depleted tumor tissues." (PMID 33352874, 2020). "In multivariate Cox proportional hazard model analysis, age, LNM, tumour size, and FABP5 were found to be independent prognostic factors." (PMID 32550890, 2020). "The most extensively studied FABP in PCa, FABP5, promotes PCa cell and/or xenograft tumor growth, with inhibition of both PPARβ/δ and PPARγ suppressing these effects." (PMID 33031638, 2020). "FAS and MAGL’s roles in promoting tumor metastasis in PCa are critically dependent on FABP5, which induces PPARγ transcriptional activity, pointing to a role for the FABP5-PPARγ pathway in mediating fatty acid-induced metastasis in these tumors." (PMID 33352874, 2020). "As primary CCa tumour samples can be easily obtained by transvaginal biopsy so that the expression levels of FABP5 can be tested before treatment, the combination of FABP5, BMI, and LVSI can be applied to assess LNM in CCa patients before the first treatment." (PMID 32550890, 2020). "FABP5 has also been shown to promote PCa cell invasion and tumor metastasis by facilitating PPARγ activation." (PMID 33352874, 2020). "Upregulation of fatty acid-binding protein 5 (FABP5) expression in CCa tumours was demonstrated to positively correlate with LNM." (PMID 32550890, 2020). "HCC tissues were further divided into FABP5-high or HIF-1α-high and FABP5-low or HIF-1α-low tissues; we found that elevated FABP5 and HIF-1α expression in the tumor was associated with poor tumor-free survival in HCC patients." (PMID 33128030, 2020).